SEMA6A (semaphorin 6A)
Diseases named in the same sentence as SEMA6A in open-access papers (continued):
Sharing a sentence is not in itself a finding about the gene and the disease.
lung carcinoma (continued). "For investigating the effect of SEMA6A on lung cancer cell migration, we overexpressed either the full-length DNA constructs of SEMA6A (6A-FL) or the DNA construct of the ectodomain (6Aect, residues 1-704), silenced endogenous SEMA6A in H1299 cells, and performed a transwell assay." (PMID 31527696, 2019). "Our results explain why low SEMA6A is linked to high recurrence in the clinical setting and suggest that SEMA6A could be useful as a biomarker or target in lung cancer therapy." (PMID 31527696, 2019). "Since both axonal guidance and metastasis are associated with the alteration of cell morphology and cell movement, SEMA6A may also regulate the migration of lung cancer cells." (PMID 31527696, 2019). "This newly discovered function and mechanism of SEMA6A indicates that SEMA6A may be a cancer suppressor and can be a biomarker of lung cancer." (PMID 31527696, 2019). "In addition, endogenous SEMA6A was undetectable in several lung cancer cell lines, including A549, H1299, H1975, H441, and H520." (PMID 30518871, 2018). "Overexpression of SEMA6A increased apoptosis in both lung cancer cells and normal lung fibroblasts." (PMID 30518871, 2018). "Through our study we aimed to identify the pleiotropic effects of SEMA6A in lung cancer cells, which could be regarded as a potential therapeutic target for lung cancer treatment." (PMID 30518871, 2018). "However, the functions of SEMA6A in lung cancer cells are still unclear." (PMID 30518871, 2018). "Semaphorin 6A (SEMA6A), a membrane-bound protein, is downregulated in lung cancer tissue compared to its adjacent normal tissue." (PMID 30518871, 2018). "The results described so far are the first evidence that the cytosolic signaling mediated by the cytosolic region of SEMA6A can induce apoptosis and is regulated by the SEMA domain in lung cancer cells." (PMID 30518871, 2018). "To test this hypothesis, we compared the migration capability of H1299 lung cancer cells with and without SEMA6A overexpression." (PMID 31527696, 2019).
oral cancer (5 papers, 2021 to 2025). "Additionally, SEMA6A has been shown to be associated with tumor apoptosis in human oral cancer cell experiments." (PMID 37434634, 2023). "For example, anti-cancer miR-203 directly targets SEMA6A to trigger apoptotic cell death in oral cancer cells." (PMID 35269749, 2022). "A study showed that miR-203 induces the apoptosis of YD-38 human oral cancer cells by directly targeting semaphorin 6A (SEMA6A), suggesting its potential application in anticancer therapeutics." (PMID 33806361, 2021). "Downregulation of SEMA6A induced apoptosis in human oral cancer cells." (PMID 41259456, 2025).
diabetes (4 papers, 2019 to 2023). "miR-27b augments bone marrow-derived angiogenic cell function in diabetes by suppressing Sema6A expression, leading to accelerated wound healing." (PMID 35045890, 2022). "Functionally, molecular analysis of sciatic nerve tissues showed that SC-Exo treatment reversed diabetes-reduced miR-21, miR-27a, and miR-146a levels, as well as diabetes-increased Semaphorin 6A (SEMA6A), PTEN, and nuclear factor-κB (NF-κB) levels." (PMID 32708290, 2020). "Further analysis revealed that SCEVs were able to reverse the diabetes-induced reduction in several essential miRNAs, such as miR-21, -27a, and -146a, along with the modulation of a diabetes-induced elevation in semaphorin 6A (SEMA6A), RhoA, PTEN, and nuclear factor-kappa B (NF-kB)." (PMID 38139147, 2023). "Patients with diabetes exhibit decreased expression of miR-27b, which directly targets Sema6a mRNA." (PMID 35045890, 2022). "Here, we found diabetes reduced NRP1 transcripts in bone marrow pericytes and increased SEMA6A (p < 0.05 vs non-diabetic control individuals for both comparisons), a known angiogenesis inhibitor." (PMID 31001672, 2019). "Diabetes induced an increase in immunoreactive ANGPT2 (p < 0.05) but did not alter ANGPT1, VEGFA, VEGFB, IGFBP2 or SEMA6A." (PMID 31001672, 2019).
glioblastoma (3 papers, 2019 to 2025). The most malignant astrocytic tumor (WHO grade IV). "Irradiation and Atm loss were associated with changes in the expression of semaphorin genes specifically, semaphorin 6A (Sema6a) and semaphorin 3D (Sema3d) which have been implicated in the tumor cell proliferation and survival in glioma mouse models and in glioblastomas." (PMID 40244686, 2025).
brain ischemia (2 papers, 2010 to 2023). Diminished or absent blood supply to the brain caused by obstruction (thrombosis or embolism) of an artery resulting in neurologic damage. "We conclude that semaphorin 6a overexpressed in the cortex enhances recovery after cerebral ischemia." (PMID 20505770, 2010).
clear cell renal cell carcinoma (2 papers, 2023 to 2025). "In clear cell renal cell carcinoma (ccRCC), SEMA6A expression is upregulated, and its overexpression promotes the malignant phenotype of ccRCC." (PMID 41259456, 2025). "However, the role of SEMA6A in clear cell renal cell carcinoma (ccRCC) is unclear." (PMID 36739418, 2023).
colorectal cancer (2 papers, 2008 to 2025). A primary or metastatic malignant neoplasm that affects the colon or rectum. "The importance of Sema6A expression in pontine nuclei is, however, called into question by analyses of mutants in Netrin-1 or its receptor, deleted in colorectal cancer (DCC)." (PMID 19063725, 2008).
glioma (2 papers, 2025). A benign or malignant brain and spinal cord tumor that arises from glial cells (astrocytes, oligodendrocytes, ependymal cells). "In comparison to normal tissue, spatial enrichment for SMOC1, ACAN, and SEMA6A transcripts was evident in cells of grade 2 glioma samples." (PMID 41366031, 2025).
hepatocellular carcinoma (2 papers, 2021 to 2025). A malignant tumor that arises from hepatocytes. "A reduction in SEMA6A mRNA expression inhibited the progression of hepatocellular carcinoma." (PMID 41259456, 2025).
ovarian carcinoma (2 papers, 2020 to 2022). A malignant neoplasm originating from the surface ovarian epithelium. "For example, overexpression of Semaphorin-6A (SEMA6A) is correlated with TUBB3/βIII-tubulin upregulation in ovarian cancer cells, while the reverse is observed in SEMA6A knockdown cells." (PMID 35573698, 2022). "Likewise, levels of the transcription factor ZEB1 have also been shown to influence TUBB3 expression in ovarian cancer in the same manner as Semaphorin-6A." (PMID 35573698, 2022). "However, in contrast to our results, downregulation of SEMA6A was observed in the DOX-resistant A2780 ovarian cancer cell line." (PMID 32283808, 2020).
pancreatic cancer (2 papers, 2012 to 2021). "In addition, it could promote the migration of pancreatic cancer cells by targeting Sprouty2 and increase endothelial cell sprouting by regulating the expression of the angiogenesis inhibitor semaphorin 6A (SEMA6A)." (PMID 23240057, 2012).
type 2 diabetes (2 papers, 2022 to 2025). "SEMA6A gene is positively associated with 9 pathways such as natural killer cell-mediated cytotoxicity, type 2 diabetes and other pathways." (PMID 41329689, 2025). "In type 2 diabetes, inhibition of miR-27a/b, which targets the angiogenesis repressor SEMA6A, promotes better healing of diabetic wounds." (PMID 36362280, 2022). "Previous reports have linked the TEAD1, HECW1, SEMA6A, COL13A1 and LAMA2 genes with different age-related cancers, the PLAT and ACE genes with cardiovascular disease, the ACE and HECW1 genes with Alzheimer’s disease and the SEMA6A gene with type 2 diabetes." (PMID 36362280, 2022).
age-related macular degeneration (1 paper, 2014). Age-related loss of vision in the central portion of the retina (macula), secondary to retinal degeneration. "Additionally, miR-27expression has been linked to a number of diseases, such as neovascular age-related macular degeneration (AMD), where it has been reported to promote abnormal angiogenesis of the blood vessels behind the eye, by targeting the angiogenesis inhibitors SEMA6A and SPROUTY2." (PMID 25369332, 2014).
Anxiety (1 paper, 2011). Intense feelings of nervousness, tension, or panic often arise in response to interpersonal stresses. "The effect on anxiety in Sema6A mutants is particularly interesting in light of the strong association of PLXNA2 variants with anxiety in humans." (PMID 22132072, 2011). "Sema6A mutants show an anxiolytic profile across two measures of anxiety-related behaviour, which cannot be explained with reference to the observed hyper-exploratory phenotype." (PMID 22132072, 2011). "Emotionality and anxiety-related behaviour were examined in Sema6A−/− mice in the elevated plus maze." (PMID 22132072, 2011). "When tested in an alternative assay of anxiety, marble-burying behaviour, both male and female Sema6A−/− mice demonstrated an anxiolytic phenotype, as measured by fewer marbles buried, relative to wild-type controls (t39 = 2.17, p<0.05)." (PMID 22132072, 2011). "Male Sema6A−/− mice demonstrated decreased anxiety, as evidenced by increased percent time spent in the open arms relative to the enclosed arms of the maze (WT vs. Sema6A−/−: t18 = 2.36, p<0.05)." (PMID 22132072, 2011). "Mice mutant for the Sema3E gene also demonstrate reduced anxiety in the elevated plus maze, which may be attributable to a defect in the fornix of these animals, suggesting a similar possible explanation in Sema6A mutants." (PMID 22132072, 2011).
Autoimmunity (1 paper, 2021). The occurrence of an immune reaction against the organism's own cells or tissues. "The functions of semaphorin 6A, encoded by this gene, are not well-characterized, and its role in the risk for GPA remains unclear, but a possible link points to the involvement of semaphorins in the immune response in autoimmune disorders." (PMID 34621800, 2021).
choroidal neovascularization (1 paper, 2018). An eye disorder described by the growth of new blood vessels that originate from the choroid through a break in the Bruch membrane into the sub–retinal pigment epithelium (sub-RPE) or subretinal space. "A recent study also demonstrated that knockdown of miR-27, which downregulates the antiangiogenic factors Sprouty2 and semaphorin 6A (Sema6A), is protective against laser-induced choroidal neovascularization." (PMID 29560091, 2018).
colon cancer (1 paper, 2023). "Moreover, we demonstrated XIST and its targets NDRG1 and SEMA6A to be significantly repressed in clinical samples (Fig. 5B2) and provided evidence for hypermethylation of NDRG1 and SEMA6A in colon cancer clinical samples (Fig. 5B3)." (PMID 37208732, 2023). "Following the combined decitabine/PBA treatment of colon cancer cells, we observed a highly significant sixfold induced expression of XIST and a three- and twofold induction, respectively, of its target genes NDRG1 and SEMA6A." (PMID 37208732, 2023).
ischemia (1 paper, 2010). A hypoperfusion of the BLOOD through an organ or tissue caused by a PATHOLOGIC CONSTRICTION or obstruction of its BLOOD VESSELS, or an absence of BLOOD CIRCULATION. "Semaphorin 6a was regulated during the recovery phase following ischemia in the cortex." (PMID 20505770, 2010).
kidney cancer (1 paper, 2023). Primary or metastatic malignant neoplasm involving the kidney. "We also found that SEMA6A is highly expressed in kidney cancer cell lines compared to most other cancer types exploring the Cancer Cell Line Encyclopedia (CCLE) database." (PMID 36739418, 2023).
Parkinson disease (1 paper, 2025). A progressive degenerative disorder of the central nervous system characterized by loss of dopamine producing neurons in the substantia nigra and the presence of Lewy bodies in the substantia nigra and locus coeruleus. "Finally, we investigated the correlation between immune cell ratios and CD4 and SEMA6A expression in Parkinson’s disease patients to identify biomarkers associated with immune cell ratios." (PMID 41329689, 2025). "Although traditionally studied for its role in axonal guidance and neuronal migration within the central nervous system, our finding that SEMA6A is significantly upregulated and functions as an immune-related gene points to a novel periphery-driven mechanism in Parkinson’s disease (PD) pathogenesis." (PMID 41329689, 2025). "In this study, we identified seven hub genes—PI3, TMSB15A, CLEC4M, CD4, SEMA6A, PLXND1, and AVP—that collectively drive Parkinson’s disease progression through synergistic mechanisms." (PMID 41329689, 2025).
pituitary hormone deficiencies (1 paper, 2023). "Interestingly, our patients do not exhibit other pituitary hormone deficiencies, strongly supporting a selective effect of SEMA6A on the regulation of the HPG axis." (PMID 38062045, 2023).
psychosis (1 paper, 2011). "Importantly, the hyperlocomotion in Sema6A mutants, as in these other models, is reversible by treatment with antipsychotics, demonstrating the predictive validity of this phenotype as a model for psychosis and differentiating it from hyperlocomotion induced by drugs such as nicotine." (PMID 22132072, 2011). "The amphetamine sensitisation model, which directly alters dopaminergic signalling and which is well accepted as a model of psychosis, is also characterised by an EEG phenotype that is highly similar to that observed here in Sema6A mutants – namely, a selective increase in alpha power." (PMID 22132072, 2011).
Stroke (1 paper, 2019). Sudden impairment of blood flow to a part of the brain due to occlusion or rupture of an artery to the brain. "The amount of mRNA of Sema6a, assessed as the percentage of signal over background, showed an ubiquitous increase throughout the spinal GM of the stroke-denervated hemicord compared with sham-operated control animals (DH: **p = 0.004, VH: **p = 0.0028, CPA: **p = 0.0081, two-way ANOVA with MC)." (PMID 30962276, 2019). "Furthermore, four upregulated candidates were addressed in this study as potential stroke-induced growth-promoters: Sema6a, Ntng2, GDF7, and TGF-β1." (PMID 30962276, 2019). "Thus, Sema6a might positively regulate the growth of CSMN sprouts into the stroke-denervated spinal target area." (PMID 30962276, 2019). "For three upregulated genes of the late phase, Sema6a, Ntng2, and TGF-β1, the potential to overcome spinal cord extract mediated growth-inhibition was shown in an in vitro neurite outgrowth assay, suggesting their role as growth-promoters in the spinal GM after stroke." (PMID 30962276, 2019).
tumor (23 papers, 2008 to 2026). "For example, recent publications have identified mTOR signaling and the SEMA6A/RHOA/YAP axis as off-target mechanisms in BRAFi-associated tumor-protective effects of fibroblasts in the TME." (PMID 38839106, 2024). "In lung cancer, a loss of two chromosome regions containing semaphorins 3p21.3 (SEMA3B and SEMA3F) and 5q21–22 (SEMA6A) is associated with the inhibition of proliferation and invasion of tumor cells and angiogenesis." (PMID 34209679, 2021). "In this context, low expression of Sema6A was associated with a larger tumor volume, as well as shorter time to recurrence and overall survival, featuring an independent prognostic factor for GBM patients." (PMID 33537086, 2021). "The results of the present research suggested that the Linc00511–hsa-miR-625-5p–SEMA6A axis could be associated with tumor autophagy, drug resistance, and cell apoptosis in SKCM." (PMID 37434634, 2023). "Functional assays illustrate that SEMA6A overexpression exerts anti-tumor effects both in vitro and in vivo, while integrated RNA-seq and proteomic analyses identify ISG15 as a key downstream effector negatively regulated by SEMA6A." (PMID 42303907, 2026). "Collectively, these findings highlight the potential of SEMA6A as a dual therapeutic strategy in CRC: inhibiting cancer progression while enhancing anti-tumor immunity by targeting the ISG15/TGF-β1 axis." (PMID 42303907, 2026). "In summary, SEMA6A overexpression alleviated CRC progression by inhibiting tumor growth and metastasis both in vivo and in vitro." (PMID 41259456, 2025). "By analyzing a variety of tumor tissues, it was found that only SEMA6A, which is highly expressed in SKCM, resulted in reduced overall survival (OS)." (PMID 37434634, 2023). "Consistent with the in vitro results, SEMA6A depletion decreased the subcutaneous tumor volume, size, and weight." (PMID 36739418, 2023). "Several semaphorins including Sema3a, Sema3f, Sema3g and Sema6a have been reported to exert tumor growth-inhibiting activities while several others such as Sema4d and Sema6d have been associated with tumor-promoting functions in various cancer types." (PMID 35223842, 2022). "As an inhibitor of tumor angiogenesis, SEMA6A regulates vascular development by regulating signal transduction of endothelial growth factor receptor (VEGFR)-2." (PMID 34869051, 2021). "Importantly, SEMA6A overexpression reshapes the tumor microenvironment, boosts anti-tumor immunity of CD8+ T cells and inhibits immune evasion, thereby potentiating anti-PD-1 immunotherapy in vivo." (PMID 42303907, 2026). "We subsequently explored the role of SEMA6A in CRC tumor growth in vivo." (PMID 41259456, 2025). "Moreover, searching the online UALCAN database revealed that the mRNA expression level of SEMA6A in different pathological stages and tumor grades of ccRCC was higher than that in normal renal tissues." (PMID 36739418, 2023). "This study demonstrates that Semaphorin 6A (SEMA6A) is downregulated in CRC tissues, with low SEMA6A expression correlating with increased tumor aggressiveness and poor prognosis in CRC patients." (PMID 42303907, 2026). "Lastly, intraperitoneal administration of recombinant extracellular SEMA6A in mouse inhibited both bFGF/VEGF and tumour cell line-induced neovascularisation." (PMID 18781179, 2008). "In addition, SEMA6A expression is increased in renal cell lines, and recombinant soluble racemic cell domains inhibit basic fibroblast growth factor (bFGF/VEGF) and tumor cell-induced neovascularization." (PMID 34869051, 2021). "We found that Sema6A-depletion in BRAFV600E clones and primary tumor cells results in cell death." (PMID 25576923, 2015). "To investigate the role of Sema6A in BRAFV600E cells, we carried out siRNA experiments, with different Sema6A-specific silencing sequences (siSema6A) in three clones isolated from 665/2 cell line and in one cell line (10538) isolated from a BRAFV600E primary tumor." (PMID 25576923, 2015).
tumor (continued). "Moreover, the SEMA6A gene is expressed in certain tumor cells and promotes their growth independent of cell adhesion." (PMID 36362280, 2022). "Furthermore, NGS analysis revealed that NF-κB/RELA targets including CCL2, CXCL8, EDN1, IL-1β, IL-6, and SERPINE1 were further reduced and several potential tumor suppressors, such as FABP3, FADS2, FDFT1, SEMA6A, and PCK2, were synergistically induced by the Gefitinib-+IKK16 treatment." (PMID 36358633, 2022). "They investigated the expression in the TME of 3 Plexin-A4 ligands, namely Sema3A, Sema6A, and Sema6B, and found that none of them modulated CD8+ T cell infiltration into the tumor bed." (PMID 38329122, 2024).